CD4 (CD4 molecule)
Diseases named in the same sentence as CD4 in open-access papers (continued):
Sharing a sentence is not in itself a finding about the gene and the disease.
infection (continued). "We estimated that 45% of those living with undiagnosed HIV in the EU/EEA in 2016 had a CD4 cell count of > 500 cells/mm3, which suggests a relatively shorter duration of infection in this group." (PMID 29208159, 2017). "As shown for a group of HIV-infected mice, the average percentage of CD4+ T cells decreases by 13% during the first two months post-infection (p.i.)." (PMID 28558649, 2017). "During HIV and murine infection with the persistent clone-13 (Cl-13) strain of lymphocytic choriomeningitis virus (LCMV), depletion of CD4 T cells is associated with reduced CD8 T cell effector functions and increased viral titers." (PMID 28715493, 2017). "infection, CD4+ intraepithelial lymphocytes (IELs) produce IFNγ which is essential for innate immunity and adaptive TH1 immune responses and has a direct inhibitory effect on Cryptosporidium spp." (PMID 29295550, 2017). "Following the experimental infections, we first compared the proliferation of antigen experienced CD4+ T cells." (PMID 29312315, 2017). "We therefore examined if infection of LC with HHV-8 affects their ability to induce naive CD4+ T cell proliferation in an allogeneic mixed-lymphocyte reaction (allo-MLR)." (PMID 28768873, 2017). "Depletion of TRIM5α in primary LCs, or a Langerhans-like cell line (MUTZ-LCs), resulted in increased infection and enhanced transmission to cocultured CD4+ T cells." (PMID 29056936, 2017). "The time lag from infection of the CD4+ T-cells to the cells becoming actively infected was included in the model." (PMID 29349288, 2017). "As SAMHD1 is also highly expressed in activated CD4+ T-cells that support productive infection, several studies demonstrated posttranslational modification as a means of mechanistic regulation of SAMHD1 function in restricting HIV-1." (PMID 29176984, 2017). "Our results provide evidence demonstrating that CD4 T cells from T. cruzi infected mice exhibited an increase in GRAIL expression during the acute phase of infection, which was correlated with defects in proliferation and immune responsiveness." (PMID 28114324, 2017). "The transmission rate is thought to be much lower and there is a longer period of asymptomatic infection with a slower decline in CD4 cell counts." (PMID 28259182, 2017). "Infection of CD4+ T cells is the key difference between HIV-1 and other infectious pathogens and activated CD4+ T cells are the primary targets for HIV-1, thus a narrow spectrum of epitope presentation by a protective allele appears to make sense." (PMID 28893268, 2017). "We previously reported that endogenous A3H mRNA expression levels in primary human CD4+ T cells are significantly lower than those of anti-viral A3 genes such as A3D, A3F, and A3G, and that activation and/or infection stimuli induces higher A3H expression." (PMID 28475648, 2017). "Recent observations of CD4+ T cell exhaustion in chronic viral infections suggest that CD4+ T cells are also crucial for optimal infection control." (PMID 28629373, 2017). "The two sulfopeptides of the eCD4-Ig dimer and at least one of its CD4 domains engage Env to provide high avidity binding and prevent enhancement of infection observed with CD4-Ig." (PMID 29253851, 2017). "Previous studies have shown that chronic immune activation plays a critical role in HIV pathogenesis, contributing, besides direct infection, to progressive destruction of the CD4 T cell compartment and to the dysfunction of multiple immune cell subsets." (PMID 28346521, 2017). "NK cells produce IFN-gamma rapidly during infections, which is essential to drive the differentiation of CD4+ T cells and induce adaptive immune responses." (PMID 28488245, 2017). "CD4+ T cells play a pivotal role in the development of effective humoral immunity to infections by helping B cells and also cellular immunity by helping CD8+ T cells, as well as in the regulation of the immune system." (PMID 28553284, 2017).
infection (continued). "Compared to HIV-1NL43, HIV-1ZAC replication in CD4+ T cells on day 14 post infection was ~100-fold lower." (PMID 28288662, 2017). "The reduction from 60% to 36% infection among memory CD4 T cells in one lymph node sample when vRNA was excluded is consistent with a substantial vRNA contribution." (PMID 28654687, 2017). "Although GS-9620 was inactive against HIV in purified CD4+ T cells and macrophages, the coincubation of isolated CD4+ T cells with conditioned medium derived from PBMCs pretreated with GS-9620 24 h prior to infection resulted in a potent antiviral response." (PMID 27799218, 2017). "In the presence of allogeneic CD4+ T lymphocytes the infection of DCs increased strongly, reaching >10% of the DCs in case of BaL, demonstrating functionality of the studied virus preparations." (PMID 28348557, 2017). "During infection, such cells are converted to memory-like T cells to maintain a pool of central memory-like CD4+ T cells in secondary lymphoid organs." (PMID 28439500, 2017). "The results showed that following the infection, the frequency of CD4+ T Foxp3+ cells were reduced in both infected groups at fourth wpi compared with respective naïve littermate control group." (PMID 28775724, 2017). "Recently, we demonstrated that infection of BALB/c mice with Plasmodium yoelii resulted in an expansion of naturally occurring CD4+Foxp3+ regulatory T cells (Tregs)." (PMID 28293237, 2017). "The significance of Siglec-1-mediated capture of virions by macrophages and of VCC formation itself is most likely in providing a storage or transport compartment for infectious virions that mediate trans-infection of CD4+ T lymphocytes." (PMID 28129379, 2017). "Upon infection of CD4+ T-lymphocytes, HIV integrates into the host genome and exploits cellular resources to produce viral progeny." (PMID 28462923, 2017). "IL-10 plays an important role in the regulation of P. yoelii infection, and CD4+ T cells have been shown to secrete high amounts of IL-10 upon infection." (PMID 28293237, 2017). "CD4+ cells were the biggest population within IL-10+ T cells throughout infection, with Treg cells representing only a minor population of IL-10–expressing CD4+ T cells." (PMID 28584007, 2017). "Further evidence can be found in in vitro infection of lymph node histocultures with HIV-1 that results in activation of CD4 and CD8 T cells characterized by upregulation of CD25 and HLA-DR." (PMID 28829402, 2017). "Infections with parasitic nematodes lead to the instruction of type 2 immune responses marked by the differentiation of naïve CD4+ T cells into T helper type 2 (Th2) cells." (PMID 28676845, 2017). "To test the contribution of TNFα to bacterial killing by CD4+IFNγ-/- T cells we isolated naïve and immune CD4+ T cells from R. typhi-infected BALB/c IFNγ-/- mice on day 7 post infection and incubated these cells with R. typhi-infected macrophages in vitro." (PMID 28222146, 2017). "We then assessed the presence of HIV RNA transcripts in different CD4+ T cell subsets after ex vivo infection of unstimulated and unfractionated PBMCs from healthy donors." (PMID 28698276, 2017). "In this model, both CD4+ and CD8+ T cells proliferated in response to infection, with CD4+ T cells becoming most enriched, and both cell types displaying markers of memory differentiation." (PMID 28398253, 2017). "In T. cruzi-infected muMT mice, TNF-producing cells are mostly CD4+ T cells, implying that B cells condition the CD4+ T cell response during the infection." (PMID 29209313, 2017). "Using LLO:I-Ab and 2W:I-Ab tetramers, we enriched specific CD4+ T populations from the cell suspensions prepared from spleen and lymph nodes at several time points following infection(s)." (PMID 29312315, 2017). "Studies with L. major in the resistant C57Bl/6 mouse model showed that early in the infection distinct CD4+ T cell populations with memory potential emerge." (PMID 29312315, 2017).
infection (continued). "In contrast to recent reports that CD4 CAR transduced CD8 T cells are susceptible to infection by cell-free virus, we were only able detect intracellular Gag in CAR+ CD8 T cells after diluting to low E:T ratios with HIV-infected CD4 T cells." (PMID 29023549, 2017). "Based on the years post infection and CD4 counts, they were categorized into ART-naïve 20 LTNPs and 18 progressors." (PMID 29250072, 2017). "Conversely, when infected with a high-dose aerosol inoculum (HDA, ~1,000 bacilli per mouse), C57BL/6 and Ob/Ob mice established an infection resulting in an early influx of IFN-γ+ CD4+ T cells in the lungs." (PMID 28421165, 2017). "The development of early and multi-specific class 1 CD8+ and class II CD4+ T cell and NAb responses during acute HCV infection are associated with the spontaneous clearance of infection." (PMID 29163442, 2017). "It is thought that the infection takes place during the peripheral interaction between CD4 and CD8 as part of an immune response, thereby allowing direct transmission of HIV-1 to the CD8 lymphocytes." (PMID 29088095, 2017). "The T cell component includes 14 CD8 T cell epitopes from early antigens and 4 CD4 T cell epitopes, targeted during the course of a natural infection and providing a population protection coverage of over 95% and 81.8%, respectively." (PMID 29119120, 2017). "SIVmac239 infection induced a more dramatic decrease in the naïve CD4+ T cell count (67.0 cells/μl) in old ChRM compared with young macaques (202.8 cells/μl, P = 0.0009)." (PMID 28232735, 2017). "ICS-assays revealed the presence of APP-CCE specific CD4+CD8αdim IL-17A-producing T cells in blood and lung tissue in most infected animals during the acute and chronic phase of infection and a minor fraction of these cells co-produced TNF-α." (PMID 28166835, 2017). "Listeria monocytogenes bacteria were detected in the livers of 8 of the 14 Nfatc1f/fx CD4-cre mice infected with ΔActA Lm-Ova for 5 d whereas only two of the WT mice showed signs of infection." (PMID 28894104, 2017). "Self-reactive CD4+ T cells differentiate into Th17 cells, which promote production of auto-antibodies and auto-inflammation, implying that infections can trigger autoimmunity." (PMID 28449694, 2017). "P2X7 deficiency in CD4 T cells resulted in a lower increase in the TE, TEM and TCM cell populations a month after infection." (PMID 28859168, 2017). "There are multiple potential sources of endogenous IL-27, and while macrophages and DCs are considered major contributors, a more recent report suggested that during infection with Plasmodium berghei CD4+ T cells also produced IL-27." (PMID 28129374, 2017). "To investigate Hobit expression after primary hCMV infection, we analyzed CD4+ T cells in samples derived from three hCMV-seronegative recipients who had received hCMV-positive kidney transplants at least 35 weeks ago." (PMID 28392788, 2017). "We previously demonstrated that the F3 protein of NH36 hosts the immunodominant CD4+ epitopes necessary for protection against L. chagasi and L. amazonensis infections." (PMID 28280494, 2017). "Virus production in human immunodeficiency virus 1-infected individuals is largely the result of a dynamic process involving continuous rounds of de novo infection and replication in CD4 T cells with rapid turnover of both free virus and virus-producing cells." (PMID 28265271, 2017). "In RV144 trial analysis, vaccinees with polyfunctional CD4+ T cell responses against HIV peptides were found to have a lower rate of infection." (PMID 28223987, 2017). "Effective depletion of neutrophils at early time points in combination with CD4+ T cell depletion resulted in a persisting infection that was significantly higher than in mice depleted of CD4+ T cells alone." (PMID 28739831, 2017). "In WT mice, we found that BM CD4+ T cells increased in number 24-fold on infection, whereas CD8+ T cells increased ~2-fold." (PMID 28671989, 2017).
infection (continued). "Inhibition of Snapin enhanced localization of HIV‐1 with TLR8+ early endosomes, triggered a pro‐inflammatory response, and inhibited trans‐infection of CD4+ T cells." (PMID 28923824, 2017). "It is also important to have a valid and accurate documentation of clinical data (such as CD4 count and virus load) to correct falsely identified recent or long-standing infections, as is recommended internationally." (PMID 28693564, 2017). "This raises several questions for the regulation of the F. hepatica CD4 T-cell response; herein, we examined the hepatic lymph node (HLN) CD4 T-cell pool for functional capacity during chronic patent infection with F. hepatica." (PMID 28871261, 2017). "CD4+ T cells appear critical in limiting pathogen further growth in the early stage of intracellular infection, whereas CD8+ T cells are particularly important in the later stage of infection." (PMID 28592247, 2017). "Several Chlamydia studies have determined that interferon gamma (IFNγ)-producing CD4 T cells play a direct protective role during infection, as bactericidal IFNγ targets C.t. while it is intracellular." (PMID 28567043, 2017). "We further validated the expression of some of the most prominently modulated genes from different cell cycle phases in CD4+ T cells from two seronegative donors post-infection." (PMID 28184007, 2017). "Most likely, the lack of chemokine receptors affects the activation and homing of Th1 CD4 T cells to genital track, which are pivotal for eliminating infection." (PMID 29552679, 2017). "Conversely, if a CD4+ T-cell enters quiescence shortly after infection, proviruses within or near T-cell activation and metabolic genes should be more likely to become silenced in tandem with the cellular genes due to changes in the local chromatin." (PMID 28727807, 2017). "CD4+ T cells were then purified from the lungs of these mice at around 4 weeks of infection, near the peak of the T cell response." (PMID 29066547, 2017). "The slow late decay (phase 2) is likely due to infection of resting CD4+ T-cells, which then progress slowly to provirus integration." (PMID 28678879, 2017). "Regarding CXCR4-tropic HIV, CXCR4 has been reported to be an absolute requirement for infection of resting CD4+ T cells purified from HIV-positive patients’ blood." (PMID 29085362, 2017). "Subsequent migration of DC to lymph nodes is thought to promote infection of CD4+ T cells by transfer of the virus, in a process called trans-infection." (PMID 29056936, 2017). "The observation that still 70% of R. typhi-infected CB17 SCID mice that received IFNγ-/- CD4+ T cells survived the infection was surprising." (PMID 28222146, 2017). "We identified a total of 21 EBV-specific CD4 T cell epitopes from the relevant epitope databases that were elicited in the course of a natural infection by EBV in humans." (PMID 29119120, 2017). "30–90% of R typhi-infected CB17 SCID mice that receive these cells survive the infection although showing prolonged disease compared to mice that are substituted with wild-type CD4+ T cells." (PMID 28770333, 2017). "The CD4+ T cell count can also be used to determine the stage of infection (Yeghiazarian, Cumberland & Yang, 2013)." (PMID 28970973, 2017). "Viruses using CCR5 are largely transmitted and endure throughout infection and those that use CXCR4 often emerge later on in the course of infection and have been associated with more rapid disease progression and CD4 cell decline." (PMID 28240046, 2017). "We found that the frequency of IL-10-producing CD4+ T cells was increased by both infection and PTP inhibition." (PMID 28710387, 2017). "After 7 days of infection, autologous CD4+ T cells were added (3 cells/MDM), and transmission allowed to proceed for an additional 12 hours." (PMID 28129379, 2017). "The hepatic CD4/CD8 ratio gradually decreased as the infection dose increased; it was lower in HDG than in LDG and MDG at 24 weeks (p = 0.0013; p = 0.0181)." (PMID 28894272, 2017).
infection (continued). "Adult worms are rapidly cleared after challenge infection due to a highly polarized Th2 immune response critically dependent on IL-4-producing CD4+GATA3+ T cells, alternatively activated macrophages (AAMØ), B cells, and parasite-specific IgG1." (PMID 28968468, 2017). "Alterations in the phenotype of these unconventional naïve CD4 T cells in PsA suggest adoption of memory properties similar to that observed following infection but are also present in healthy individuals at low frequencies." (PMID 29163483, 2017). "Taken together, these findings highlight the need to initiate ART early-on during infection and maintain adequate levels of CD4+ T cells." (PMID 28362068, 2017). "In contrast, perforin expression in IL-7Rneg CD4+ T cells was high in the first month after infection (60% of cells produced perforin); this perforin expression subsequently decreased." (PMID 29112951, 2017). "Administration of tamoxifen prior to secondary infection successfully reduced the expression of IL-4Rα on mediastinal lymph node (mdLN) CD4+ T cells in iCre-/+IL-4Rα-/Lox mice compared to control that were given vegetable oil." (PMID 28651009, 2017). "HIV infection leads to major perturbations on immune system regulatory mechanisms as CD4 T cells depletion, maturation and exhaustion of T cells and a constant immune activation are hallmarks of this infection." (PMID 28346521, 2017). "The engagement of the HIV-1 gp120 glycoprotein to the host CD4 protein triggers conformational changes in gp120 that allow its binding to co-receptors and is necessary for virus entry to establish infection." (PMID 28743743, 2017). "Very high titers of anti-HIV IgG antibodies are a hallmark of infection, strongly suggesting that there is significant HIV-specific CD4+ T cell help to HIV-specific B cells." (PMID 28553284, 2017). "Our data showed distinct CD4+ T helper (Th) polarization and cytokine dysregulation in response to F. gigantica infection in water buffaloes over the course of infection." (PMID 29216911, 2017). "Bacterial numbers were reduced in all CD4+IFNγ-/- T cell recipients including those that succumbed to the infection." (PMID 28222146, 2017). "Others found no or limited effect on bystander activation of naïve CD4+ T cells, but showed bystander activation of memory CD4+ T cells, similar to what was shown in infection for CD8+ T cells and which was mostly attributed to maintenance of memory." (PMID 28489886, 2017). "Two additional key findings were presented in this work: first, a significant proportion of CD4+ and CD8+ T cells have their PD-1 expression upregulated during infection with WT parasites, in contrast to infection caused by hrfΔ parasites." (PMID 28831137, 2017). "Together, our findings show an important role of both memory CD4+ T cells and macrophage infection, specifically in spleen or BM." (PMID 28279181, 2017). "Both Th2 and ex-Foxp3 Th2 cells were able to passively transfer immunity to normally susceptible Hp 1° hosts, resulting in a significant reduction in the establishment of infection, compared with mice receiving naive CD4+ T cells." (PMID 28507062, 2017). "The group transferred with WT CD4+ T cells eliminated more bacteria, which indicated that memory CD8+ T cells generated by CD4+ T-cell antigen presentation also cleared bacteria efficiently during secondary infection." (PMID 29147022, 2017). "As an indicator for the activation of adoptively transferred T cells we further analyzed serum cytokine levels on day 7 post infection in control mice, CD4+ and CD8+ T cell recipients." (PMID 28222146, 2017). "While evidence does suggest the protective role of CD4 CTL induced early after infection, less work has focused on determining the efficacy of vaccine-induced CD4 CTL in humans." (PMID 28167943, 2017).